CXCL12 (C-X-C motif chemokine ligand 12)
Diseases named in the same sentence as CXCL12 in open-access papers (continued):
Sharing a sentence is not in itself a finding about the gene and the disease.
pancreatic cancer (continued). "CXCL12 stimulation also induces resistance to chemo- and radiotherapy by maintaining and stimulating CXCR4-expressing adhesive cancer cells in a protective microenvironment like the bone marrow, as has been recently confirmed for hematological malignancies and pancreatic cancer." (PMID 36725964, 2023). "Interestingly, AMD3100 reduced the proliferation of Hs766t, a CXCL12+ KRAS wild-type (WT) pancreatic tumor cell line, suggesting an autocrine regulatory loop that may be at play in some pancreatic tumors." (PMID 35008248, 2021). "Intriguingly, CXCL12 also altered non-migratory functions of pancreatic cancer cells, with stable re-expression of the liganddecreasing population growth via cell-cycle arrest in vitro and correspondingly smaller tumor xenografts with decreased proliferation markers in vivo." (PMID 24594697, 2014). "In pancreatic cancer cells, the α6β1 and α3β1 integrins interact with laminin-1 to mediate cell migration; this process involves the upregulation of CXC chemokine receptor 4 (CXCR4) and IL-8 expression in response to the chemokine ligand CXCL12, also known as stromal cell-derived factor-1 (SDF-1)." (PMID 24490159, 2013). "Furthermore, high concentrations of CXCL12 are present at the common sites of pancreatic metastases (lymph nodes, liver, lungs, and so on), suggesting that CXCL12–CXCR4 signalling may have a role in the homing of pancreatic cancer cells to specific organs." (PMID 21045835, 2010). "Our retrospective analyses of the INT-11 trial consisting of 660 pancreatic cancer patients demonstrate that tipifarnib may sensitize PDAC to gemcitabine in a patient population stratified based on the absence of abdominal pain as a surrogate for high CXCL12 expression." (PMID 35008248, 2021). "CXCL12 activates both canonical and non-canonical GPCR pathways in pancreatic cancer cell lines." (PMID 22472349, 2012). "However, correlations between the CXCL12/CXCR4 axis and clinical features of pancreatic cancer have not been extensively studied." (PMID 23181100, 2012).
glioma (160 papers, 2008 to 2025). A benign or malignant brain and spinal cord tumor that arises from glial cells (astrocytes, oligodendrocytes, ependymal cells). "In a post-hoc exploratory analysis of tumor tissue, higher frequency of CXCL12+ endothelial and glioma cells was significantly associated with longer PFS under NOX-A12." (PMID 38806504, 2024). "CXCL12 has been implicated in the progression of glioblastoma, with the expression of CXCL12 rarely identified in low-grade gliomas." (PMID 33803414, 2021). "Another SVZ-released molecule implicated in the stimulation of glioma invasion is CXCL12 (C-X-C motif chemokine 12)." (PMID 33330101, 2020). "In glioma, the receptor, CXCR4, and its ligand, CXCL12, have been implicated in this mechanism in rat and patient glioma cells." (PMID 31632905, 2019). "In NF1-associated low-grade gliomas, CXCL12 also serves as a paracrine factor that drives the growth of neoplastic Nf1−/− astrocytes." (PMID 28380429, 2017). "In this manuscript we provide evidence that CXCL12 signaling involved in chemotaxis of glioma cells is tightly linked to PDGFR signaling since inhibiting CXCR4 activation impairs PDGF-induced chemotaxis and vice versa." (PMID 24023874, 2013). "Moreover, neuron-derived cytokines such as IL-6 and chemokines like CXCL12 have been implicated in promoting glioma proliferation, immune evasion, and stem-like cell recruitment." (PMID 40999491, 2025). "The angiogenic switch of CNS tumors, which allows for recurrence of glioma, its quick progression and malignant transformation toward higher grades, may be also associated with proangiogenic CXCL12 activity." (PMID 34200145, 2021). "Glioma cell lines (U87, SHG-44, and CHG-5) and human primary glioma specimens express higher levels of CXCL-12 and CXCR4 mRNA." (PMID 40727443, 2025). "The receptor CXCR7 has been recently identified as a second receptor for CXCL12, and its expression has been shown to be increased in gliomas cells." (PMID 39715221, 2024). "CXCL12 was highly expressed in pericytes, endothelial and myeloid cells, and, at a very minimal level, also in glioma cells." (PMID 39272976, 2024). "Our results are supported by a recent preclinical study that identified high endothelial CXCL12 expression as a key chemokine involved in pro-tumorigenic remodeling of the glioma microenvironment." (PMID 38806504, 2024). "Analyzing publicly available single-cell RNA sequencing (scRNAseq) data from human GBM35 showed the highest level and frequency of CXCL12 mRNA expression in endothelial cells, followed by pericytes, myeloid (macrophages, microglia), and glioma cells." (PMID 38806504, 2024). "Datasets from CGGA and our paired grade IV gliomas consistently revealed that CXCL12 was positively correlated with PD-L1 expression." (PMID 38898023, 2024). "For example, the Notch signaling pathway promotes invasion, self-renewal, and proliferation of glioma-starting cells via controlling the chemokine system CXCL12/CXCR4." (PMID 38203782, 2024). "While endothelial cells showed the highest relative CXCL12 positivity, the total number of endothelial cells was roughly twelve times lower than that of glioma cells." (PMID 38806504, 2024). "Although no significant change of net distance was observed in NSC (p = 0.32), antagonist for CXCR4 have blocked CXCL12‐mediated iPSC‐NSC pathotropism toward glioma cells." (PMID 37693056, 2023). "CXCL12 is also able to attract CXCR4 + myeloid derived suppressor cells to create an immunosuppressive microenvironment that favors the growth of glioma, as reported for other tumors." (PMID 38293652, 2023). "These immune cells had the highest density in gliomas and possessed immunosuppressive cytokines and chemokines, including CXCL12, CXCL10, CCR5, CCR10, CCL5, and CCR2, to exert their immunosuppressive effects." (PMID 37515314, 2023).
glioma (continued). "Glioma infiltration of the subventricular zone is also related to C-X-C motif chemokine receptor type 4 (CXCR4)/C-X-C motif chemokine ligand 12 (CXCL12 or stromal derived factor-1, SDF-1)." (PMID 35204054, 2022). "CXCR7 has been recently identified as a second receptor for CXCL12, and its expression has been shown to be increased in many tumor cell lines, including gliomas cells." (PMID 35745762, 2022). "In glioma cell lines KCa3.1 expression level correlates with cell invasiveness in response to the chemokine CXCL12, serum, and bradykinin." (PMID 36589283, 2022). "In gliomas, abnormal expression profiles of CXCL9, CXCL10, CXCL11, and CXCL12 were noticed among different pathological grade gliomas, implying their potential relationship with glioma progression." (PMID 34603309, 2021). "One report has shown that in cultured primary astrocytes and human glioma cells, CXCL12 induced ACKR3 mediated increases of intracellular calcium and pertussis toxin sensitive ERK and AKT signaling suggesting ACKR3 activates Gi/o." (PMID 34583741, 2021). "An increased expression of CXCR4 mRNA and CXCL-12 levels has been observed in human primary glioma specimens and glioma cell lines (U87, SHG-44, and CHG-5)." (PMID 34439380, 2021). "Gliomas have been shown to actively recruit TAMs by releasing several factors, including SDF-1 (CXCL12, C-X-C Motif Chemokine Ligand 12), and M-CSF (CSF-1; Colony Stimulating Factor 1)." (PMID 32570988, 2020). "It was also observed that CXCR4 is highly expressed in glioma progenitor cells, whereas its ligand CXCL12 promotes a specific proliferative response in these cells." (PMID 32456359, 2020). "CXCR7 is present on tumor endothelial, glioma and microglial cells, and is often colocalized with CXCL12." (PMID 32098047, 2020). "Another chemokine that plays a crucial role in the growth and proliferation of gliomas is CXCL12, whose activity is mediated through conventional chemokine receptor CXCR4." (PMID 32456359, 2020). "Since it is well known that CXCL12 activates members of the MAP kinase family in gliomas via its G-protein-coupled receptors CXCR4 and CXCR7, it seems obvious that CXCL12 regulated CCL2 and SAA2 expression during cellular dormancy entry via these pathways." (PMID 32346064, 2020). "Using immunohistochemical techniques in glioma tissues obtained in total tumor resection, it was demonstrated that CXCL12 was expressed mainly in vascular endothelial cells, while CXCR4 immunostaining was observed mainly in tumor cells." (PMID 32456359, 2020). "(c) The expression of CXCR4 and CXCL12 in high grade glioma tissues through immunohistochemistry analysis." (PMID 31382985, 2019). "Because glioma cells themselves can express CXCL12, it has been proposed that one way interstitial flow stimulates invasion is through a mechanism termed “autologous chemotaxis”1,5,6,29." (PMID 30451884, 2018). "In vitro, flow-stimulated invasion was mitigated by both blocking the receptor CXCR4 as well as saturating the ligand CXCL12, suggesting this chemokine-receptor pathway plays a key role in glioma cell flow response." (PMID 30451884, 2018). "CXCL12 is also a potent chemotactic agent for lymphocytes and can induce an increase in monocyte-macrophage infiltration into the glioma microenvironment MC infiltration in the glioma TME leads invariably to a tissue inflammation." (PMID 28445977, 2017). "ZEB1 is associated with malignancy in glioma and analysis of GBM patient specimens demonstrated that proinflammatory cytokines, such as CXCL12, IGFBP2, IL-1ß, TNF-a and MIF, correlate significantly with ZEB1 expression in tumor specimens." (PMID 28445977, 2017). "Alternatively, hypoxia, which usually develops in the tumour core region progressively with the growing tumour mass, leads to an increase in CXCR7 expression in the microvascular endothelium and ultimately enhances CXCL12-dependant glioma cell migration." (PMID 29113105, 2017).
glioma (continued). "This was also corroborated by Liu and colleagues who suggested that glioma cells which express CXCR7 were shown to migrate toward CXCL12 gradients in close vicinity to blood vessels of highly vascularised glioma tumours." (PMID 29113105, 2017). "The CXCR4/CXCL12 molecular axis is involved in numerous responses that drive glioma progression, such as tumor cell proliferation, survival, angiogenesis, invasion and migration." (PMID 28423060, 2017). "Numerous studies on preclinical glioma models have shown that the blockade of the CXCL12/CXCR4 axis by specific antagonists affects tumor growth, vasculogenesis and post-radiation recurrence." (PMID 28423060, 2017). "In our study, we observe a marked increase in the expression of CXCL10 and CXCL12 in the glioma cells after co-culture as compared to normal culturing of glioma cells." (PMID 28445977, 2017). "The CXCR4/CXCL12 axis is particularly active in pseudopalisading areas surrounding the necrotic foci and in invading glioma cells." (PMID 26880981, 2016). "Consistently, post-radiation therapy inhibition of CXCL12/CXCR4 interaction resulted in the inhibition of tumor recurrence in glioma models." (PMID 27015814, 2016). "In fact, it was demonstrated that exogenous CXCL12 can induce glioma cell proliferation and that CXCL12-dependent initiation of ERK1/2 and AKT pathways is involved in the transduction of proliferative signals in normal and tumor glial cells." (PMID 26880981, 2016). "Another study reported a direct tropic interaction of human glioma U87-Luc cells with CXCL12-expressing endothelial cells which was blocked by CXCR4 antagonists but not CXCR7 antagonists." (PMID 27863376, 2016). "CXCL12 (or SDF-1) is constitutively expressed in the CNS on blood vessels and astrocytes and is also found expressed in and around transplanted gliomas." (PMID 26291724, 2015). "CXCR4/CXCL12 growth stimulating effects were also detected in glioma stem cells via an AKT-mediated prosurvival and self-renewal pathway." (PMID 25110692, 2014). "The CXCL12 pathway is a key receptor system in the cross-talk between tumor cells and the vasculature in glioma." (PMID 25084358, 2014). "This is exemplified by observations in human glioma in which CXCR4/CXCL12 interaction favors an autocrine or paracrine loop for tumor cell proliferation." (PMID 25110692, 2014). "Conversely, the glioma onco-suppressive gene LRRC4 inhibits CXCL12/CXCR4-induced cell proliferation, chemotaxis and invasiveness reducing ERK1/2 and Akt signaling." (PMID 24904289, 2014). "CXCR7-expressing U87MG, LN229 and LN308 glioma cells migrated towards stromal-derived factor (SDF)-1α/CXCL12 in hypoxic conditions in the Boyden chamber assays." (PMID 23865743, 2013). "We have previously demonstrated that glioma migration induced by CXCL12 is specifically abolished by inhibitor of KCa3.1, with mechanisms independent of those activated by EGFR." (PMID 24023874, 2013). "The migratory behaviour of GBM cells is known to be conditioned by a number of tissue- and glioma-derived cytokines and growth factors and among these, CXCL12 modulates different aspects of glioma biology, including migration." (PMID 24023874, 2013). "The quantification revealed that up to 95% of endothelial cells are indeed CXCL12 positive in both Ntv-a Arf−/− and Gtv-a Arf−/− mouse gliomas." (PMID 21949886, 2011). "In the in vitro migration assay CXCL12 neutralization in glioma-conditioned medium led to a significant decrease of MC migration." (PMID 21949886, 2011). "Similar to mouse gliomas, MCs in the human gliomas showed a predominantly perivascular localization and stained positive for both CXCL12 and CXCR4." (PMID 21949886, 2011). "Taking into account that the CXCL12/CXCR4 interaction has a pronounced role in development of tumor vasculature, and that CXCL12 is a known MC chemotaxin, we demonstrated that both mouse and human gliomas were highly positive for CXCL12." (PMID 21949886, 2011).
glioma (continued). "This suggests that glioma cells, in accordance with the results from the MC migration assay, are the primary source of CXCL12 production and hence attract MCs via a CXCL12/CXCR4 axis." (PMID 21949886, 2011). "Despite being expressed by glioma cells at a higher level, CXCL12 is additionally expressed by endothelial cells further increasing its chemotactic potential." (PMID 21949886, 2011). "It has been previously shown, that CXCL12 was expressed by glioma cells and its expression increased with increasing tumor grade." (PMID 21949886, 2011). "After adding the CXCR4 agonist CXCL12, glioma cell lines were prevented from apoptosis and showed increased chemotaxis." (PMID 18781150, 2008). "Furthermore, the PI3K/Akt signaling pathway was activated by chemokine (CXCL-12) to induce CD133+ glioma stem-like cells to produce more vascular endothelial growth factor (VEGF), thereby increasing angiogenesis and metastasis." (PMID 40727443, 2025). "In addition, post-hoc tumor tissue analyses suggest improved clinical efficacy of this CXCL12-inhibiting L-RNA aptamer in a subgroup of patients characterized by a high frequency of CXCL12 positivity of endothelial and glioma cells." (PMID 38806504, 2024). "Chemoattractants for microglia released by macrophages include Hepatocyte growth factor/scatter factor released by glioma cells, while CXCL12 (SDF-1) is also a potent microglia and macrophage recruiting molecule, especially for attracting TAMs to hypoxic areas." (PMID 38672638, 2024). "The results indicate that the microglia may be involved in the treatment of central nervous system cancer pain mediated by CXCL12/CXCR4." (PMID 39641645, 2024). "CXCR4/CXCL12 signaling promoted tropism of NSCs toward glioma cells." (PMID 37693056, 2023). "Glioma cells also release CXCL12 and overexpress its receptor CXCR4." (PMID 38293652, 2023). "Since CXCR4 is the corresponding receptor for the cytokine CXCL12 expressed by glioma tumor cells, it is suggested that mast cells may be attracted to the tumor via the CXCL12/CXCR4 axis." (PMID 38275375, 2023). "Additionally, recent studies showed that chemokine receptor type 4 (CXCR4) and C-X-C motif chemokine ligand 12 (CXCL12) promoted glioma cells to acquire more invasive phenotypes." (PMID 35053605, 2022). "It is demonstrated that the endogenous stem cell factor (SCF) largely contributes not only to the expansion of the glioma-associated MCs but also to the localization of the MCs in the vicinity of the tumor blood vessel and glioma cells along with the CXCL12/CXCR4 axis." (PMID 34671362, 2021). "Furthermore, chemokine (CXCL-12) was found to increase vascular endothelial growth factor (VEGF) production by CD133+ glioma stem-like cells via the activation of the PI3K/Akt signaling pathway, resulting in enhanced angiogenesis and metastasis." (PMID 34439380, 2021). "Finally, glioma CSCs have been shown to secrete stromal cell-derived factor 1 (SDF-1/CXCL12) in order to recruit MSCs." (PMID 33059744, 2020). "CXCR4 and CXCL12 are the potent regulators of glioma stem cell proliferation." (PMID 32456359, 2020). "CCX733 also decreased the antiapoptotic effects of CXCL12 in glioma cells." (PMID 32098047, 2020). "In the last decade, several preclinical studies in glioma models have shown that the impairment of the CXCL12/CXCR4 signaling using specific antagonists reduces tumor growth, angiogenesis, and recurrence, suggesting that this approach represents a promising strategy for GB therapy." (PMID 30123112, 2018). "It was postulated that this effect was due to increases in both CXCR4 and CXCL12 in glioma cells." (PMID 30451884, 2018). "SDF-1 (CXCL12) is a well-known glioma cell-derived factor essential for GAM recruitment." (PMID 29389898, 2018). "In turn, CXCL12 is widely produced in gliomas and normal brain." (PMID 30123112, 2018).